TGFA (transforming growth factor alpha)
Diseases named in the same sentence as TGFA in open-access papers (continued):
Sharing a sentence is not in itself a finding about the gene and the disease.
gastric tumours (1 paper, 2017). "Expression of the TGFα protein was reported in most studies in between 35 and 74% of gastric tumours." (PMID 27933395, 2017).
glaucoma (1 paper, 2023). Increased pressure in the eyeball due to obstruction of the outflow of aqueous humor. "Indeed, high levels of IL8, VEGFA, PDGF, TGFB1, and TGFA have been found in AH of glaucoma patients." (PMID 37569323, 2023).
granulosa cell tumor (1 paper, 2012). A slow-growing, malignant tumor, characterize by the presence of granulosa-like cells and Call-Exner bodies, that is almost always found in the ovary. "Taken together, these findings suggest that TGFα may be involved in granulosa cell tumor initiation and progression." (PMID 23155381, 2012).
Headache (1 paper, 2020). Cephalgia, or pain sensed in various parts of the head, not confined to the area of distribution of any nerve. "Transforming Growth Factor α (TGFα) and Interleukin-33 were found to inversely correlate with headaches in the ME/CFS EV samples (r = −0.66, p = 0.002 and r = −0.63, p = 0.005 for TGFα and IL-33 respectively), and these correlations were unique in patients with ME/CFS compared to the control group." (PMID 33046133, 2020).
hemangioblastoma (1 paper, 2020). "Overexpression EGFR and TGFα may contribute to tumor growth in VHL-related hemangioblastomas." (PMID 32432044, 2020). "However, at present, the role of EGFR and TGFα in VHL-associated hemangioblastomas has not been examined." (PMID 32432044, 2020).
hypothalamic hamartomas (1 paper, 2019). "Interestingly, human hypothalamic hamartomas associated with sexual precocity in humans contain numerous astrocytes expressing TGFα and erbB1 receptors." (PMID 30893295, 2019).
inflammatory bowel disease (1 paper, 2019). A spectrum of small and large bowel inflammatory diseases of unknown etiology. "Of note, CD patients who improved with QBECO treatment also had increases in their levels of TGFα, which has been reported to be reduced in diseased regions of the colon of patients with inflammatory bowel disease and increased in healthy regions." (PMID 31380382, 2019).
keratosis (1 paper, 2024). A skin disorder consisting of hypertrophy of the stratum corneum of the skin. "The GSEA results also show that TGFA is significantly enriched in many pathways associated with keratosis." (PMID 38152044, 2024).
Lipedema (1 paper, 2022). Disorder of adipose tissue characterized by symmetric and bilateral enlargement of the lower extremities due to abnormal deposition of subcutaneous fat often in obese women. "For instance, the cytokines VEGFA, TGFα and TGFβ1 were among the inflammatory markers upregulated in lipedema." (PMID 36387874, 2022).
malignant glioma (1 paper, 2004). A grade III or grade IV glioma arising from the central nervous system. "Epidermal growth factor receptor and its main ligands EGF and transforming growth factor alpha (TGFα) are commonly overexpressed in malignant glioma." (PMID 15305185, 2004).
metastasis (1 paper, 2017). The spread or migration of cancer cells from one part of the body (where they first appeared) to another. "Regarding the general prognostic value of TGFα, data are quite inconsistent; high TGFα levels in the tumour were correlated with lymph node metastasis, poor overall survival, advanced TNM stage and tumour size in some studies." (PMID 27933395, 2017).
myocardial infarction (1 paper, 2014). Gross necrosis of the myocardium, as a result of interruption of the blood supply to the area, as in coronary thrombosis. "Herrmann and colleagues found that preconditioning with TGFα led to an enhanced cardioprotective role for MSCs, and MSCs preconditioned with a cytokine cocktail, including TGFβ, were shown to be beneficial for restoring cardiac function in a model of myocardial infarction." (PMID 25376815, 2014).
pancreatic ductal adenocarcinoma (1 paper, 2015). An infiltrating adenocarcinoma that arises from the epithelial cells of the pancreas. "While overexpression of TGFα has been reported in human pancreatic ductal adenocarcinoma (PDAC), mice with overexpressed TGFα develop premalignant pancreatic acinar-to-ductal metaplasia (ADM) but not PDAC." (PMID 25803032, 2015).
papilloma (1 paper, 2010). A benign epithelial neoplasm that projects above the surrounding epithelial surface and consists of villous or arborescent outgrowths of fibrovascular stroma. "TGFα null and wa-1 keratinocytes transformed with the v-H-ras oncogene and grafted onto nude mice give rise to skin tumors (mostly papillomas) similar to that of keratinocytes from BALB/c or C57BL mice (wild-type counterparts to wa-1 or TGFα null, respectively)." (PMID 21297902, 2010). "Transgenic mice that overexpress TGFα in the skin via either a K14 or keratin 1 (K1) promoter develop papillomas upon wounding or with TPA treatment without carcinogen initiation, demonstrating that high expression levels of TGFα can act as an initiating event, as well as enhance tumor promotion." (PMID 21297902, 2010).
polycystic kidneys (1 paper, 2025). "In addition, transforming growth factor alpha (TGF-alpha) is often found to be overexpressed in human polycystic kidneys." (PMID 40801635, 2025).
psychosis (1 paper, 2023). "Furthermore, data about inflammatory biomarkers in patients with dual diagnosis (psychosis and addiction) are reported in scientific literature and TGFα has been proposed as a potential biomarker of this double condition." (PMID 36830990, 2023).
rectal cancer (1 paper, 2017). A primary or metastatic malignant neoplasm that affects the rectum. "However, in patients with rectal cancer, TGFα levels, but not EGF levels, increased during cetuximab treatment, and this increase was correlated with T downstaging." (PMID 27933395, 2017).
relapsing-remitting multiple sclerosis (1 paper, 2025). The most common clinical variant of multiple sclerosis, characterized by recurrent acute exacerbations of neurologic dysfunction followed by partial or complete recovery. "To further investigate a still-prevailing deficit of TGFα, we assessed TGFα levels in cerebrospinal fluid (CSF) samples obtained from treatment-naïve patients diagnosed with relapsing-remitting multiple sclerosis (RRMS) and controls with non-inflammatory disease." (PMID 40537468, 2025).
salpingitis (1 paper, 2022). Acute or chronic inflammation of the fallopian tube. "Females having adhesions in the Fallopian tubes (salpingitis; SA) revealed positive relationships between inhibin and TGFα (0.97; p = 0.03), inhibin and glucose (0.99; p = 0.007), and TGFα and glucose (0.98; p = 0.02)." (PMID 36009715, 2022).
schwannoma (1 paper, 2023). A benign, usually encapsulated slow growing tumor composed of Schwann cells. "Our studies suggest that pS6 may be a specific biomarker of Nrg1 but not TGFα production in schwannoma." (PMID 36944680, 2023).
selenium deficiency (1 paper, 2013). A nutritional deficiency disease resulting from inadequate selenium levels in the body, which can lead to impaired function of selenoproteins essential for antioxidant defense and thyroid hormone metabolism. "Overall, TGFα played a far more dominant role in liver tumor induction than selenium deficiency or reduced stress-related selenoprotein expression in the present study." (PMID 23460847, 2013).
serous ovarian carcinoma (1 paper, 2023). "In high-grade serous ovarian carcinoma (HGSOC), a high level of transforming growth factor alpha (TGFα) was directly related to the modulation of differentiation of monocytes into M2-like macrophages and, thereby, tumor transformation." (PMID 37443711, 2023).
skin tumor (1 paper, 2010). "TGFα expression is elevated in mouse skin tumors induced by DMBA initiation and promoted with either TPA or chrysarobin." (PMID 21297902, 2010). "Single and multiple applications of various skin tumor promoters up-regulate epidermal expression of TGFα." (PMID 21297902, 2010).
spinal cord injury (1 paper, 2025). Penetrating and non-penetrating injuries to the spinal cord resulting from traumatic external forces (e.g., WOUNDS, GUNSHOT; WHIPLASH INJURIES; etc.). "As a member of the epidermal growth factor (EGF) family, TGFα induces astrocyte proliferation and increases neuronal survival, migration and axonal growth in multiple contexts, including models of spinal cord injury (SCI) and ischemic stroke." (PMID 40537468, 2025).
stricture (1 paper, 2025). "MDK–NCL, CXCL5/6‐CXCR2, and TGFA–EGFR ligand–receptor pairs were enhanced in stricture tissues, mediating epithelial–stromal interactions." (PMID 39910700, 2025).
vaginitis (1 paper, 2022). A non-infectious or infectious inflammatory process affecting the vagina. "In females that suffered from vaginitis (VA), there were found significant positive relationships between inhibin and TGFα (0.76; p < 0.05), IL-β and TGF-α (0.79; p < 0.05), free T3 and free T4 (0.77; p < 0.05), DHEA and free T3 (0.75; p < 0.05) and between E2 and P4 (0.88; p = 0.009)." (PMID 36009715, 2022).
Venous malformation (1 paper, 2023). A vascular malformation resulting from a developmental error of venous tissue composed of dysmorphic channels lined by flattened endothelium and exhibiting slow turnover. "Epidermal growth factor receptor (EGFR)/ErbB1 ligand transforming growth factor A (TGFA) is upregulated in venous malformation (VM) and angiomatosis of soft tissue (AST) patient tissue samples." (PMID 37199488, 2023). "(C–E) Correlation between transforming growth factor A (TGFA) and HIF1A (C), HIF2A (D), and VEGFA (E) mRNA expression levels detected in angiomatosis of soft tissue (AST) and venous malformation (VM) lesions (n=23)." (PMID 37199488, 2023).
tumor (336 papers, 1987 to 2026). "A previous study showed that TGFA is involved in the differentiation of tumor-associated macrophages (TAMs)." (PMID 35774505, 2022). "At cut-off value >50%, the expression of TGFα was also significantly associated with tumours <G3 (P = 0.028)." (PMID 30899442, 2019). "In the vascular system, they influence the migration of tumour cells, the liberation of cytokines and growth factors linked to the cellular membrane, such as the transforming growth factor alpha TGF-α and the epidermal growth factor EGF." (PMID 26913068, 2016). "We then sought direct evidence that the decreased tumor cell growth associated with RHBDD1 inactivation was due to decreased TGFα/EGFR signalling." (PMID 26300397, 2015). "Here we showed that systemic and local metabolic alterations caused by a deficiency of the metabolic regulator FGFR4 reduce TGFα-induced tumor incidence and progression in breasts where FGFR4 expression is negligible." (PMID 24279986, 2013). "For example, overexpression of the EGFR agonist transforming growth factor alpha (TGFα) in mice causes hepatic hyperplasia and tumour formation, and EGFR is upregulated in a majority of human hepatocarcinomas." (PMID 22967907, 2012). "TP38, a similar molecule with TGFα linked to a 38 kDa fragment of PE, was tested in Phase I trials of malignant brain tumors with intracranial infusion techniques utilized for treatment delivery directly to tumor tissue." (PMID 27153091, 2016). "TGFα can activate mitogenic pathways; so, this finding highlights the potential risk that these compounds could promote tumor growth." (PMID 26779438, 2015). "We found that the number of lymphatic vessels in EGFR-expressing tumors was fourfold higher than that observed in EGFR-deficient tumors, demonstrating that TGFα-EGFR signaling is an important cofactor for expansion of the tumor-associated lymphatic vascular network." (PMID 23986907, 2013). "TNF-α is associated with cell-cycle progression, tumor growth, and oxidative stress, stimulating the expression of Transforming Growth Factor alpha (TGF-α) in mouse hepatocytes and the formation of 8-oxodeoxyguanosine, a critical biomarker of oxidative stress and carcinogenesis." (PMID 23533994, 2013). "The pathway analysis indicated alterations in PI3K/Akt, MYC and NF-κB signaling pathways, and potential critical roles for TGFA, ErbB2, and IL-1/IL-1R which may promote angiogenesis, tumor growth, and metastasis and hence cause the aggressive phenotype observed in young women." (PMID 23704896, 2013). "Therefore the persistent survival of an alveolar population from one pregnancy through the next represents a premalignant population that exhibits an increased predisposition for tumor development for mice transgenic for mammary-specific transforming growth factor alpha (TGF-α)." (PMID 17626637, 2007). "In this study, FABP4, PPARGC1A, AGPAT4, ALDH1A1, and GPAT3 were identified as downregulated tumor suppressor genes in TC, whereas TGFA was recognized as an oncogene." (PMID 40119647, 2025). "Functional assays using RNA interference and CRISPR/Cas9 demonstrated that TGFA knockdown significantly impaired cell proliferation, reinforcing the critical role of TGFα in driving tumor growth." (PMID 40410803, 2025). "Its pathophysiology implicates tumor-secreted peptides—notably transforming growth factor alpha (TGF-α)—that stimulate epidermal hyperplasia via epidermal growth factor receptor (EGFR) activation." (PMID 41357602, 2025). "HB-EGF and TGFα, whose upregulation in various cancers has been shown to contribute to metastatic and invasive behavior and tumor progression, were chosen and revealed higher levels in XTCCs based on one or both cell lines." (PMID 41308994, 2025). "Further, ETS-1 can inhibit transforming growth factor alpha (TGF-α) expression, thereby restoring tumor cell proliferation in vivo and promoting autonomous growth in culture." (PMID 40181983, 2025).
tumor (continued). "While canonical EMT is well-studied in cancer progression, the hEMT state—marked by co-expression of epithelial (e.g., CDH1, IRF6, JUP) and mesenchymal (LAMC2, ITGB4, TGFA) genes—has emerged as a driver that enhances cellular plasticity and tumor metastasis." (PMID 40777467, 2025). "Excess secretion of pro-inflammatory cytokines (e.g. IL-6, IL-1β, TGFα) by immune cells is critically involved in tumour cell avoidance of immune surveillance in the tumour microenvironment as well as in inflammation." (PMID 41023585, 2025). "We found that exposure to FGF2, FGF18, HBEGF, IGF1, PDGF-BB, and TGFα significantly (p < 0.0001) increased MCL1 expression in tumor cells (by at least 1.2-fold and up to 2-fold) and treatment with the MEKi reduced this response." (PMID 37676378, 2024). "Down‐regulated expression of TGFA can decrease the viability of tumour cells and decrease the ability of metastasis and invasion of tumour cells." (PMID 38152044, 2024). "Analysis of ligand-receptor pairs revealed interactions between CXCR1+ neutrophils and tumor cells involving TGFA-EGFR and EGF-EGFR, potentially explaining aspects of resistance to third-generation EGFR-TKIs due to sustained EGFR activation." (PMID 39638994, 2024). "Our work highlighted the crucial role of the tumor cell-rCAF crosstalk in contributing to cancer chemoresistance through the TGFα-EGFR paracrine signaling pathway." (PMID 37821657, 2023). "To demonstrate the clinical relevance of our findings, we co-immunostained tumor tissue sections derived from chemo-sensitive and -resistant patients with TGFα and α-SMA antibodies." (PMID 37821657, 2023). "We revealed that TGFα-EGFR carcinogenic action is being enhanced in BC cases of low WWOX expression which is supposed to be a very common event in this tumor." (PMID 35290621, 2022). "TGFα is widely expressed in both normal epithelium and tumour cells and it is considered a ligand for EGFR." (PMID 35681586, 2022). "In the TGFα/c-myc model, tumor lesions and liver tissues contained similar amounts of AAV vector genomes, arguing against a preferred accumulation in tumor lesions due to morphological changes of the organ upon tumorigenicity." (PMID 35053588, 2022). "TGFA is highly expressed in cancers of the digestive tract, the reproductive system, and the lungs, with the levels recovered to normal after tumor resection." (PMID 32020849, 2021). "In fact, tumor TGFα was membrane anchored, while that expressed by normal kidney tissue was proteolytically processed." (PMID 34399807, 2021). "The protein expression of CD44, HK3, KIF20A, and IDUA was higher in the tumor tissues compared to the normal tissue, and the protein expression of GALM and TGFA was lower in tumor tissues than normal, which was consistent with our results in TCGA." (PMID 33816274, 2021). "In summary, circTAF4B positively regulates TGFA expression and promotes tumor growth and EMT in vivo." (PMID 34322376, 2021). "TGFA has been previously confirmed as a crucial oncogenic mediator and promotes tumor cell growth via the TGF-α/EGFR signaling pathway." (PMID 34079795, 2021). "Together, the combined expression of TME-derived (TGFB and IGF1) and HCC-tumor derived (TGFA) upstream regulators of HSC activation suggests both the HCC tumor cells and TME cells are promoting collagen deposition." (PMID 33995488, 2021). "Our findings add TGFα as a novel factor that tumor cells can use to directly promote macrophage differentiation." (PMID 33069212, 2020). "TGFα binds to the EGFR receptor and is a potent angiogenic factor, forming an autocrine or juxtacrine loop to promote tumor progression in VHL-associated renal cell carcinoma." (PMID 32432044, 2020). "Transfection with miR-144 mimics improved the sensitivity of ATC cells to cisplatin and inhibited tumor growth by suppressing (transforming growth factor alpha) TGF-α both in vitro and in vivo." (PMID 33158279, 2020).